RAMAC (RNA guanine-7 methyltransferase activating subunit)
Description:
Regulatory subunit of the mRNA-capping methyltransferase RNMT:RAMAC complex that methylates the N7 position of the added guanosine to the 5'-cap structure of mRNAs. Promotes the recruitment of the methyl donor, S-adenosyl-L-methionine, to RNMT. Regulates RNMT expression by a post-transcriptional stabilizing mechanism. Binds RNA.
Synonyms: RAM; C15orf18; FAM103A1; RAMMET; HsT19360; MGC2560
Tractability: Small molecule: a structure with a bound ligand is known. PROTAC: ubiquitination databases record sites on it.
Gene: Protein-coding gene on chromosome 15 (82,986,203 to 82,991,057, forward strand). Ensembl gene ENSG00000169612.
Subcellular location: Nucleus
Subcellular location (Human Protein Atlas): Nucleoplasm
Gene Ontology:
Molecular function: enzyme activator activity; molecular function activator activity; protein binding; RNA binding
Biological process: 7-methylguanosine mRNA capping; RNA 5'-cap (guanine-N7)-methylation
Cellular component: methyltransferase complex; mRNA cap methyltransferase RNMT:RAMAC complex; mRNA capping enzyme complex; nucleoplasm; nucleus
Genetic constraint (gnomAD): Loss-of-function variants: 7 observed, 11.52 expected, observed/expected ratio (o/e) 0.61, 90% interval 0.34 to 1.14. The synonymous counts are far from expectation, so gnomAD's model fits this gene poorly and the ratio says little. Missense variants: 80 observed, 97.29 expected, observed/expected ratio (o/e) 0.82, 90% interval 0.69 to 0.99. Synonymous variants: 17 observed, 30.55 expected, observed/expected ratio (o/e) 0.56, 90% interval 0.38 to 0.83.
Homologues: Orthologues: chimpanzee RAMAC (99% identical), macaque RAMAC (99% identical), dog RAMAC (93% identical), guinea pig Ramac (90% identical), mouse Ramac (87% identical), rat Ramac (85% identical), mouse Ramacl (72% identical). Paralogues in human: RAMACL (99% identical).
Diseases named in the same sentence as RAMAC in open-access papers:
RAMAC is named in the same sentence as 4 diseases in open-access papers, as found by Europe PMC text mining. Sharing a sentence is not in itself a finding about the gene and the disease.
RAMAC shares sentences with these, for which no sentence is quoted: cancer (2 papers); breast carcinoma (1); glioma (1); tumours (1).